NADK (NAD kinase)
Synonyms: FLJ13052; NADK1; dJ283E3.1
Tractability: Small molecule: a structure with a bound ligand is known; a high-quality ligand is known; it has a binding pocket of medium quality. PROTAC: ubiquitination databases record sites on it; its protein half-life has been measured; a small molecule that binds it is known.
Target class: Enzyme; Transferase
Gene: Protein-coding gene on chromosome 1 (1,751,232 to 1,780,544, reverse strand). Ensembl gene ENSG00000008130.
Subcellular location (Human Protein Atlas): Nucleoplasm; Cytosol
Pathways (Reactome):
Metabolism: Nicotinate metabolism
Gene Ontology:
Molecular function: NAD+ kinase activity; protein binding
Biological process: ATP metabolic process; phosphorylation; NAD+ metabolic process; NADP+ biosynthetic process; positive regulation of insulin secretion involved in cellular response to glucose stimulus
Cellular component: cytosol
Genetic constraint (gnomAD): Loss-of-function variants: 21 observed, 48.13 expected, observed/expected ratio (o/e) 0.44, 90% interval 0.31 to 0.63. The upper end of that interval is the gene's LOEUF score, 0.63, which puts it in group 2 of 6, group 1 being the genes least tolerant of losing a copy. Missense variants: 438 observed, 623.8 expected, observed/expected ratio (o/e) 0.7, 90% interval 0.65 to 0.76. Synonymous variants: 268 observed, 261.96 expected, observed/expected ratio (o/e) 1.02, 90% interval 0.93 to 1.13.
Homologues: Orthologues: chimpanzee NADK (99% identical), macaque NADK (99% identical), dog NADK (91% identical), mouse Nadk (91% identical), rat Nadk (91% identical), guinea pig NADK (89% identical), tropical clawed frog nadk (79% identical), rabbit NADK (73% identical), pig NADK (59% identical), Drosophila melanogaster Nadk1b (55% identical), Drosophila melanogaster Nadk1a (54% identical), zebrafish nadka (37% identical).